IL22 (interleukin 22)
Diseases named in the same sentence as IL22 in open-access papers (continued):
Sharing a sentence is not in itself a finding about the gene and the disease.
Crohn disease (continued). "Earlier studies also indicated that human beta-defensins (hBDs), which are chemotactic to T cells and induce the mRNA expression of IL-1β, IL-6, and IL-22, may have copy number variations in Crohn’s disease." (PMID 38246944, 2024). "Therefore, the role of this interesting pro-inflammatory cytokine in the low-grade inflammatory response in PI-IBS merits further detailed investigation, especially because IL-22 activation is known to play a pivotal role in Crohn’s disease." (PMID 36979384, 2023). "Moreover, in a Salmonella-driven model of Crohn’s disease-like fibrosis, we showed that RORα-deficient mice were protected: RORα inactivation dampened Th17/ILC3-type cytokine production, including IL-17 and IL-22." (PMID 36052086, 2022). "While the cellular source of IL-22 may differ depending on the model, the activation of the IL-22 pathway has shown benefit in both ulcerative colitis (UC) and Crohn’s disease (CD) in mice." (PMID 34360971, 2021). "Blocking the function of IL-17A may upregulate Il6 and recruit RORγt+ ILCs in chronic colitis, thereby upregulating IL-22 and worsening the clinical outcomes of patients with Crohn’s disease." (PMID 31941937, 2020). "While intestinal CD4+ T cells represented the main source of local IL-22 in Crohn’s disease patients, IL-22-producing NKp44+ ILCs were predominant in the gut of AS patients, highlighting differences between the etiology of IBD and SpA-associated intestinal inflammation." (PMID 29922283, 2018). "Here, the plasticity of ILCs can be exploited to differentiate IFN-γ-producing CD127+ T-bet+ c-Kit− NKp44− ILC1s into IL-22-producing NKp44+ ILC3s in the presence of IL-1β and IL-23, thereby re-establishing homeostasis which may demonstrate a therapeutic effect in Crohn’s disease." (PMID 34804991, 2021). "Importantly, whereas NKp44+ ILC3, as generated in the present in vitro system, play important roles in maintaining gut integrity by producing IL-22, a pathological role is suggested for NKp44- ILC3s that produce IL-17 and are found to be enriched in Crohn’s Disease." (PMID 31861547, 2019). "It is suggested that acupuncture may not inhibit the expression of IL-17A and IL-22 in Crohn's disease model rats." (PMID 35075366, 2022). "Converse to its protective effects, IL-22 also promotes the expression of proinflammatory cytokines tumor necrosis factor (TNF)-α and IL-8 in IECs and these cytokines in turn increase IL-22R1 expression, which may further strengthen the proinflammatory effect of IL-22 in inducing Crohn's disease." (PMID 41467015, 2025).
viral infections (56 papers, 2012 to 2025). "IL-22 is thus integral in protecting the host against the lung damage caused by viral infections and preventing secondary bacterial infections." (PMID 40732672, 2025). "Previous studies found that IL-22 is substantially expressed during viral infections, and animals with deficiency of IL-22 were unable to repair and regenerate epithelial tissues." (PMID 34150807, 2021). "Our data show that IL-22 deficiency exhibits an unrelenting effect on promoting antiviral T cell responses during persistent viral infection." (PMID 28634408, 2017). "In acute and persistent viral infections, IL-22 deficiency resulted in thymic and splenic hypertrophy, while excessive IL-22 induced atrophy in these lymphoid organs." (PMID 28634408, 2017). "Our data suggest that the deficiency in IL-22 production in aged DCs could contribute to impaired epithelial repair and increased susceptibility to viral infections." (PMID 40732672, 2025). "Our findings support the hypothesis that unique cytokine signatures present in the skin, e.g., subjects with the greatest expression of IL-4, IL-13, and IL-22, would be at most risk of experiencing disseminated viral infections." (PMID 37298195, 2023). "The effect of IL-22 on KC susceptibility to viral infection is incompletely studied." (PMID 37298195, 2023). "IL-22 was associated with the expression of antimicrobial defensin proteins and the promotion of tissue barrier in intestinal epithelial cells, protecting against mucosal viral infections." (PMID 32395116, 2020). "Interestingly, basal levels of IL-18 and IL-22 were higher in Viperin−/− animals than WT animals before virus infection, suggesting a potential predisposition of these mice for INFγ-Th1 stimulation." (PMID 30665948, 2019). "Finally, we discuss the potential therapeutic utility of IL-22 manipulation in the treatment and prevention of viral infections and associated pathologies." (PMID 27303405, 2016). "In conclusion, a decline in IL-22 production from mucosal NKp44+ NK cells induced by virus infection may be one of the causes of MT in HIV/SIV infection." (PMID 25759828, 2014). "Therefore, we conclude that a decline in IL-22 production from mucosal NKp44+ NK cells induced by virus infection may be one of the causes of microbial translocation in HIV/SIV infection." (PMID 25759828, 2014). "IL-22 has emerged as a key cytokine involved in regulating host defense and epithelial repair responses during viral infection and resolution." (PMID 40732672, 2025). "During COPD progression, during bacterial and viral infections, IL-17 and IL-22 have distinct clinical significance." (PMID 41181156, 2025). "IL-22, a member of the IL-10 family produced mainly by Th1, Th17, and Th22 cells, exhibits a dual effect, “friend or foe”, in various viral infections." (PMID 40142865, 2025). "In summary, type 3 immunity, particularly involving IL-22, is crucial for defending against gastrointestinal viral infections in pigs by promoting epithelial cell responses." (PMID 39497434, 2024). "In the sublethal stage of viral infection, IL-22 plays a role in inhibiting lung inflammation, mitigating secondary infections, and maintaining the integrity of lung epithelium." (PMID 38216935, 2024). "Sc-RNAseq of PEDV-infected porcine small intestines has revealed that IL-22 is predominantly expressed by Th17 cells, with its expression significantly upregulated during viral infection." (PMID 39497434, 2024). "It is important to highlight that Interleukin-22 (IL-22) has gathered substantial attention in recent years, establishing itself as one of the most widely researched cytokines in the context of viral infections." (PMID 38216935, 2024). "Conversely, the aberrant phosphorylation of the AhR/STAT3/IL-22 axis can exacerbate viral infection and microbial translocation." (PMID 37628830, 2023).
viral infections (continued). "In response to microbial infection, IL-22 has been found to be a potent inducer of the inflammatory response, especially in viral infections, such as hepatitis B, C and HIV." (PMID 36875710, 2023). "It is important to know which signaling pathways and cytokines are induced by Th22 cells and IL-22 to predict their exact role in a particular viral infection." (PMID 37403036, 2023). "IL-22 is an important member of the IL-10 family and plays a crucial role in mounting immune responses against various viral infections." (PMID 37391858, 2023). "The proinflammatory properties of IL-22 are enhanced when synergized with IL-17 in some viral infections." (PMID 37403036, 2023). "Th22 cells and their cytokine, IL-22, have been shown to protect against various bacterial and viral infections." (PMID 37403036, 2023). "Regarding other viral infections, studies have reported IL-22 production by T cells with an antiviral protective role." (PMID 37403036, 2023). "IL-22 aimed at the treatment of viral infections has progressed very rapidly, including the regulation of ART, the IL-22/IL-22BP axis, the Notch-Th22 axis, and even the novel protein FBXW12." (PMID 36839448, 2023). "The combination of IL-18-induced apoptosis and IL-22-induced proliferation results in faster turnover of villi epithelial cells than the rate of viral infection of new cells." (PMID 35216425, 2022). "From these studies, it is concluded that IL-22 can be protective or proinflammatory, where IL-22/IL-22R axis is important for host protective immunity to both viral infections and bacterial infections." (PMID 35967401, 2022). "As the IL-22/IL-22R1 axis is involved in inflammation during virus infection, the expression patterns of IL-22/IL-22R1 on blood hematopoietic cells in SARS-CoV-2 infection have been well studied." (PMID 35967401, 2022). "During the sublethal stage of viral infection, IL-22 can inhibit lung inflammation, reduce secondary infection and preserve the integrity of lung epithelium." (PMID 35967401, 2022). "Within two days after viral infection, IL-22 gene transcription in Tγδ, Tαβ and innate lymphoid cells is also increased in lung." (PMID 35967401, 2022). "The protective effects of IL-22 in virus infections are exemplified in a study analyzing the impact of IL-22 in a setting of dengue infection." (PMID 33851257, 2021). "In this paper, we show for the first time that different immune cascades, providing crosstalk between enterocytes, macrophages, dendritic cells, fibroblasts, and T cells, are involved in the induction of IL22 in response to bacterial or viral infections." (PMID 34045640, 2021). "As for IL-22, a murine model of influenza A (IAV) viral infection followed by a secondary Streptococcus pneumoniae bacterial infection provoked an increase in RORγt+ cells and IL-22+ ILC3s in the lung." (PMID 34659248, 2021). "IL-22 is required for lung defense and repair after infection with influenza virus, as IL-22−/− mice have more severe injury after virus infection." (PMID 34504501, 2021). "2D mouse Ileum organoids were either untreated or treated for 1 day with IL22 (5 ng/ml) prior to viral infections with MHV-GFP." (PMID 34045640, 2021). "At least in enteric models of viral infection, IL-22 appears to have indirect antiviral activity against rotovirus and coronavirus in concert with IFN-λ and downstream STAT1/3 signaling, though less evidence supports similar observations in the lung." (PMID 32637365, 2020). "IL22 was identified to be regulating mucosal epithelial cell function, maintaining barrier integrity and protecting against bacterial and viral infection in the gut and lung." (PMID 33110122, 2020). "The comparable transcript levels of CXCL10, CCL2, and BCL2, as well as viral loads were observed between control and rIL-22-treated groups, indicating that IL-22 was dispensable for the growth, activation, and viral infection of human glial cells." (PMID 32843067, 2020).
viral infections (continued). "IL-22 is found to play a vital role in various viral infections by decreasing the sequelae of infection and aiding in tissue recovery." (PMID 33298930, 2020). "IL-22 has been found to regulate mucosal epithelial function by maintaining barrier integrity and protecting from bacterial and virus infection in the gut and lung." (PMID 32444639, 2020). "Our data suggest that IL-22 plays an important role in regulating mucosal and systemic immunity against bacterial and viral infection." (PMID 33178219, 2020). "IL-17 and IL-22 also promote the release of β-defensin-2 and β-defensin-3, which contribute to the immune response against bacterial, fungal, and viral infections." (PMID 33353204, 2020). "CD8+CD161+ T cells markedly enriched in the liver coexpressed IL-17 with high levels of IFN-γ and/or IL-22 and offer protection against viral infections." (PMID 33597948, 2020). "IL-22 that belongs to the IL-10 family has recently been found to play a critical protective role against viral infections in the mucosal surfaces." (PMID 32395116, 2020). "IL-22 produced by immune cells and exogenous IL-22 prevents lung tissue from acute injury induced by viral infection or ventilation trauma." (PMID 31750252, 2019). "In summary, our data demonstrate that viral infection triggers a γδ T cell-derived IL-22 production, which is mediated by the IL-23/PI3K/mTORC1 signaling pathway." (PMID 28634408, 2017). "Our data, however, revealed that IL-22 suppresses antiviral effects in T cells and subsequently impedes viral elimination during acute and persistent viral infections." (PMID 28634408, 2017). "To establish the role of IL-22 in the thymic and splenic pools during acute viral infection, we investigated the effect of IL-22 over-expression on T cell expansion and maintenance in lymphoid pools by the hydrodynamic injection of IL-22 plasmid." (PMID 28634408, 2017). "We further found that γδ T cells prominently expressed IL-22 as well as IL-17A in the liver after viral infection." (PMID 28634408, 2017). "Although the role of IL-22 in bacterial and fungal infections is well-defined, the sources of IL-22, regulatory mechanisms of its production, as well as its function in acute and chronic viral infections remain elusive." (PMID 28634408, 2017). "In this study, in response to viral infection, IL-22 production was elicited in the liver, as well as in lymphoid organs such as the thymus and spleen." (PMID 28634408, 2017). "Here, we report that viral infection triggered early IL-22 production from the liver and lymphoid organs." (PMID 28634408, 2017). "Myeloid cells such as monocytes/macrophages, neutrophils, and DCs produced negligible levels of IL-22 in viral infection." (PMID 28634408, 2017). "Although the role that IL-22 plays in bacterial and fungal infections is reasonably well-defined, a picture of how IL-22 functions in viral infections is still being constructed." (PMID 27303405, 2016). "Herein, we assess our current understanding of how IL-22 determines the outcome of viral infections and define common mechanisms that are evident from, sometimes paradoxical, findings derived from these studies." (PMID 27303405, 2016). "IL-22 was found to be involved in the control of viral infection and prevention of inflammatory injury in many diseases." (PMID 27428948, 2016). "In a number of viral infections, IL-22 signaling in the liver provides protection against virus-induced pathology without actually influencing virus replication." (PMID 27303405, 2016). "Four out of 10 mice and 3 out of 10 mice survived at 2 and 12 weeks after viral infection in anti-IL-22 treatment subgroup." (PMID 25547181, 2014). "It is noteworthy that IL-22 secretion in the mucosal NKp44+ NK cells increased dramatically with virus infection, from 5.58% (0 dpi) to 24.50% (9 dpi) in the Peyer's patches and from 3.78% (0 dpi) to 54.20% (9 dpi) in the lamina propria." (PMID 25759828, 2014).
viral infections (continued). "To investigate this, we utilized the MCMV model to elucidate the role that IL-22 plays in viral infection of peripheral tissue." (PMID 24721575, 2014). "Our data was consistent with the previous observation that IL-22 contributed to resistance to viral infection, highlighting a role for IL-22-producing Th22 cells in controlling cardiac viral replication in AVMC." (PMID 23050732, 2012). "Although IL-22 is also induced by virus and has been implicated in anti-HIV function, its in vivo role in viral infections has yet to be defined." (PMID 22952908, 2012). "Furthermore, in mammals, spleen IL-22 mRNA levels have been reported to be significantly elevated and activate disease resistance after bacterial and viral infections." (PMID 39211040, 2024). "Importantly, several reports have revealed that IL-22, a member of IL-10 family, plays a vital role in fighting against viral infections." (PMID 38216935, 2024). "IL-22 plays a substantial role in the defense against invading pathogens, such as extracellular bacteria in the lung or gut, mucosal viral infections, and intestine viral infections." (PMID 37391858, 2023). "From these two observations, we hypothesize that IL-22 alters the differentiation kinetics of KC and may keep KC in a state highly permissive to viral infection." (PMID 37298195, 2023). "Moreover, it has been reported that IL-22 can have paradoxical functions in a distinct viral infection." (PMID 37403036, 2023). "However, only deucravacitinib significantly reduced plaque number in a dose-dependent fashion in IL-22-treated KC.These results suggest cytokines utilize particular JAK pathway(s) that alter the KC response to viral infection." (PMID 37298195, 2023). "Consequently, Th22/IL-22 has both a protective and a proinflammatory role in viral infections, which is greatly affected by factors such as the subtype of virus, the severity of infection and the presence of IL-17A." (PMID 36839448, 2023). "Nevertheless, one limitation of the studies we have compiled in this review is that some results regarding the role of Th22/IL-22 in bacterial and viral infections have only been confirmed in mouse experiments, and there is no available human experimental data." (PMID 36839448, 2023). "Additionally, flagellin activates IL-22 and IL-18 activation through TLR5/NLRC4, driving IL-18-induced apoptosis of viral infection as well as IL-22-induced proliferation, thereby inhibiting viral infection." (PMID 35216425, 2022). "Numerous studies have suggested that IL-22 plays a crucial role in anti-viral infections through significantly ameliorating the immune cell-mediated inflammatory responses, and reducing tissue injury as well as further promoting epithelial repair and regeneration." (PMID 35967401, 2022). "The role of the interleukin-22 (IL-22)/interleukin-22 receptor (IL-22R) axis is well described in lung tissues, where it is essential for host protective immunity to both bacterial and viral infections." (PMID 35422799, 2022). "Of note, numerous of studies have illustrated that IL-22 plays a pivotal role in anti-viral infections through significantly ameliorating the immune cell-mediated inflammatory responses, as well as reducing lung injury and promoting further airway epithelial repair and regeneration." (PMID 35967401, 2022). "Overall, viruses can induce the expression of IL22 through an IFNβ1–IL7–IL6-axis and successively, IL22 can help defend against viral infection on different levels by regulating 1) viral degradation, 2) viral entry, and 3) viral sensitivity through sugar modifications of extracellular proteins." (PMID 34045640, 2021). "In light of these findings, it would be of interest to study whether simultaneously targeting IL-22 and IL-17A could be a potential approach for virus infection therapy." (PMID 34504501, 2021). "Intriguingly, the effects of IL-22 during viral infections in the liver seem to be dual-natured." (PMID 33851257, 2021).